ANLN (anillin, actin binding protein)
Diseases named in the same sentence as ANLN in open-access papers (continued):
Sharing a sentence is not in itself a finding about the gene and the disease.
tumor (continued). "In contrast, the expression of cytosolic ANLN was significantly higher in the metastatic foci of HCC than in the primary tumor tissue." (PMID 36553600, 2022). "Hardly any previous studies have addressed the critical relationship between ANLN and the tumor microenvironment (TME)." (PMID 36199577, 2022). "We first conducted the expression difference analysis of ANLN mRNA between tumor and normal tissues in the TCGA database." (PMID 36199577, 2022). "In the present study, we investigated the various roles of ANLN in modulating tumor immunology in some tumors." (PMID 35340220, 2022). "Our study used bioinformatics methods to further demonstrate the correlation of ANLN with tumor progression and prognosis, which provides a theoretical basis for the use of ANLN as a potential novel target for biotherapy and a biomarker for tumor surveillance." (PMID 35991576, 2022). "In order to verify the reliability of five genes in predicting prognosis, by using HPA to detect protein expression levels in normal and tumor tissues, we found that there were significant differences in ANLN and NR3C1 between tumor tissues and normal tissues." (PMID 35548187, 2022). "Our results showed that increased expression of ANLN and KIF23 was associated with higher tumor grade." (PMID 34917682, 2021). "Data from TCGA database showed that ANLN was expressed at significantly higher levels in tumor tissues thanin normal control tissues." (PMID 34082790, 2021). "ANLN has been reported to participate in the metastasis of LUAD by promoting the EMT of tumor cells." (PMID 34416861, 2021). "To further evaluate the role of the two splicing isoforms of ANLN in tumor development, we co-injected ANLN-sgRNA SCC-9 cells transfected with GFP-ANLN-201 or GFP-ANLN-210 or control, and macrophages treated with ANLN-210 mRNA-rich exosomes into the nude mice." (PMID 34344861, 2021). "ANLN was overexpressed in CRC, and the expression of ANLN was linked to tumor invasion and enlarged tumor size." (PMID 33190424, 2021). "Recent studies indicate that dysregulated ANLN contributes to the tumor occurrence, growth, and development." (PMID 34344861, 2021). "Taken together, the results reveal that the two splicing isoforms of ANLN synergistically promote tumor progression in vivo in different ways." (PMID 34344861, 2021). "ANLN expression levels correlate with the metastatic potential of human tumours from many different tissue origins as follows." (PMID 32560530, 2020). "ANLN is highly expressed in many types of site-specific cancerous tumours, including brain, lung, pancreas, and bone marrow cancer." (PMID 32560530, 2020). "The dot-box plots with data normalized for log-scale showed that ANLN expression was significantly higher in BLCA tumor samples than normal tissues (median expression 4.15 vs. 1.34, and p < 0.001)." (PMID 31766561, 2019). "In BLCA tumor samples, ANLN expression was up-regulated (median expression 16.72) compared to normal tissues (median expression 1.54), while TLE2 expression was down-regulated (median expression 22.27) compared to normal tissues (median expression 60.99)." (PMID 31766561, 2019). "We found that ANLN upregulation was significantly correlated with the tumor size (P = 0.002), tumor differentiation (P = 0.027), TNM stage (P < 0.001), lymph node metastasis (P = 0.004) and distant metastasis (P = 0.005)." (PMID 31395079, 2019). "Previous studies found that ANLN expression levels were significantly up-regulated in a variety of tumor tissues, including breast, ovarian, colon, lung, and pancreatic cancers." (PMID 31766561, 2019). "In contrast to the control group, mice injected with ANLN-depleted SMMC-7721 cells displayed greatly retarded tumor growth." (PMID 30103211, 2018).
tumor (continued). "We also evaluated the effect of ANLN depletion on tumor cell growth in vivo by subcutaneously injection of SMMC-7721 control or ANLN knockdown cells into NSI mice." (PMID 30103211, 2018). "ANLN expression was firstly compared between tumor and adjacent non-tumor tissues in 201 cases of HCC tissue samples." (PMID 30103211, 2018). "We observed overlapped ANLN expression with Ki67 in HCC tumor tissues by immunofluorescence staining analysis." (PMID 30103211, 2018). "Among these genes, we identified ANLN, overexpressed in tumor tissue, with significant prognostic value for tumor stage." (PMID 28600503, 2017). "In multivariate analysis, tumor stage (HR = 2.04, 95% CI: 1.33–4.8, p = 0.005) and ANLN expression level (HR = 2.04, 95% CI: 1.21–3.43, p = 0.007) were independent risk factors of CSS." (PMID 28600503, 2017). "ANLN expression was confirmed to be up-regulated in the majority of tumor samples (36/40), especially in MIBC, when compared with their corresponding normal tissues." (PMID 28600503, 2017). "Firstly, ANLN expression was up-regulated, with a log2-fold change of 2.926 and probability of 0.835, in tumor samples compared with corresponding normal tissues." (PMID 28600503, 2017). "Secondly, ANLN was a potential biomarker for tumor staging due to its expression level increased with BLCA stage." (PMID 28600503, 2017). "ANLN is up-regulated from 2 to 6 fold in tumor tissue, except for brain tumors, and its expression increases from normal to benign to malignant to metastatic disease." (PMID 28600503, 2017). "The expression level of ANLN mRNA was validated to be increased with tumor stage, and higher expression was indicative of poorer prognosis." (PMID 28600503, 2017). "In univariate analysis, CSS was significantly influenced by tumor stage, grade and ANLN expression level." (PMID 28600503, 2017). "To elucidate the regulatory mechanism of ANLN involved in tumor growth, we further performed flow cytometry to compare apoptosis and cell cycle phases between J82 and 5637 cells with ANLN knockdown and control cells." (PMID 28600503, 2017). "It has also been shown that depletion of ANLN expression in human non-small cell lung cancer cells leads to suppression of cell proliferation and an increase of large, poly-nucleated tumor cells." (PMID 27863473, 2016). "As a consequence of missing representative tumor tissue, the ANLN expression status was evaluated in 126/144 (87.5%) tumors in cohort I and in 358/564 (63.5%) tumors in cohort II." (PMID 27863473, 2016). "In primary NPC tissues, ANLN was expressed in the cytoplasm of NPC tumor cells (left lower), whereas HSPA4L was strongly expressed in the nucleus and cytoplasm of NPC cells and mucosa adjacent to NPC nests (right lower)." (PMID 26486082, 2015). "A scoring technique was devised attributing a score of +1 to each poor prognostic marker exhibited on immunostaining of individual tumour cores (i.e., high ANLN, high PBK and low PDZK1)." (PMID 23547718, 2013). "High ANLN protein expression were classified as tumours with a staining intensity >1, and low expression classified as tumours with a staining intensity ≤1." (PMID 23547718, 2013). "The findings showed an increase in ANLN expression in ICC tumor specimens." (PMID 41513610, 2026). "Recently, increasing studies have discovered novel effects of ANLN on tumor development." (PMID 41513610, 2026). "The mechanism underlying this involves ANLN inhibition of miR-218-5p expression through regulation of the histone methyltransferase EZH2, thereby disinhibiting the downstream target gene LASP1 and promoting tumor cell proliferation." (PMID 41573677, 2025). "In addition, we also identified a gene target, ANLN, that was most effective at preventing tumor formation." (PMID 40704506, 2025). "Furthermore, the tdTomato-positive clones were much smaller than the negative clones, again suggesting that when successful, suppression of ANLN prevented tumor development." (PMID 40704506, 2025).
tumor (continued). "In addition, a growing number of studies have found that targeting ANLN in the ceRNA regulatory network suppresses antitumor immunity in the tumor immune microenvironment and enhances multidrug resistance in tumors." (PMID 40161493, 2025). "In PAC, ANLN overexpression may promote rapid division and proliferation of tumor cells, accelerating tumor progression." (PMID 40666516, 2025). "ANLN knockdown significantly reduced glycolytic activity, tumor cell migration, and immune evasion." (PMID 40191200, 2025). "In conclusion, ANLN exhibits significant carcinogenic effects across various tumor types." (PMID 41573677, 2025). "Moreover, ANLN expression correlates with immune checkpoint molecules and the tumor microenvironment, suggesting its potential as both a prognostic biomarker and a therapeutic target." (PMID 41573677, 2025). "Tumor malignant progression mediated by ANLN and treatment resistance." (PMID 41573677, 2025). "The miR-18a levels were further used to correlate with a probability distribution of the tumour aggression score published previously which was derived by fitting a binomial logistic regression model using two genes, ANLN and BCL2, as predictors and tumour grade 3 as the determinant." (PMID 38786043, 2024). "Conversely, in human central nervous system tumors, ANLN expression is lower in tumor tissues." (PMID 38398143, 2024). "Additionally, immunohistochemistry performed on matched GBC and adjacent normal tissues showed higher ANLN levels in tumor tissues." (PMID 38398143, 2024). "In our AA prostate contralateral benign-tumor-matched cohort (n = 73), ANLN was shown to be nominally overexpressed in tumors compared to non-malignant (p = 0.06), while ECT2 was significantly overexpressed in tumor compared to non-malignant matched tissue (p < 0.00001)." (PMID 38785827, 2024). "We conducted various experiments in vivo and in vitro, which indicated that downregulating ANLN expression levels could decrease tumor cell proliferation and migration, while inducing apoptosis and cell cycle arrest." (PMID 38398143, 2024). "The miR-18a/low tumours had higher expression of the luminality-associated genes like ESR1, GATA3, FOXA1, XBP1 and TFF1 and a lower expression of the basality-associated genes such as KRT18, KRT17, FOXC1, ANLN, STIL and MIA (p < 0.05)." (PMID 38786043, 2024). "Studies have found that ANLN is involved in the occurrence and development of tumor cells." (PMID 37741887, 2023). "Finally, the precise mechanisms by which ANLN facilitates tumor progression and tumor immunity remain largely obscure." (PMID 36030492, 2023). "Subsequently, we explored the potential correlations between ANLN and tumor immune characteristics." (PMID 36030492, 2023). "Hence, we firstly explored the correlation between ANLN expression and tumor‐infiltrating immune cells." (PMID 36030492, 2023). "ANLN expression in tumor tissues of F806-treated mice was lower than that in the control group." (PMID 36526897, 2023). "In conclusion, this study constructed a prognostic model based on the MIR600HG/hsa-miR-342-3p/ANLN network and found that it may function in tumor immunity." (PMID 37741887, 2023). "The expression of ANLN in tumor tissues was higher than that in normal tissues." (PMID 37741887, 2023). "Further, it remains unclear whether ANLN is involved in different tumor immune microenvironments and can influence the therapeutic response through certain common molecular mechanisms." (PMID 35991576, 2022). "The results also suggested that ANLN expression was highly correlated with immune infiltration in LIHC; indeed, in LIHC, ANLN expression was positively correlated with tumor purity, CD8+ T cells, CD4+ T cells, B cells, neutrophils, and macrophages and negatively correlated with NK cells (P < 0.05)." (PMID 35568883, 2022). "The high ANLN expression level and elevated phosphorylation of ANLN may be potential factors for tumor progression." (PMID 35340220, 2022).
tumor (continued). "To conclude, abnormal ANLN expression may affect tumor cells’ stemness and genomic stability, thereby facilitating tumor progression." (PMID 36199577, 2022). "As a critical regulator of cell division, cell junction, and cytokinesis, it is not surprising that ANLN is closely associated with tumor initiation and progression." (PMID 36199577, 2022). "Consequently, ANLN appears to be a promising prognostic biomarker and an intriguing therapeutic target for the accurate diagnosis and precise treatment of tumor patients." (PMID 36199577, 2022). "This suggested that ANLN is crucially involved in tumor-mediated immune escape." (PMID 35991576, 2022). "We observed increased ANLN expression in multiple tumors, which could be involved in tumor cell proliferation, migration, infiltration, and prognosis." (PMID 35991576, 2022). "In the vast majority of tumor types, ANLN expression was dramatically increased." (PMID 36199577, 2022). "Accordingly, ANLN may affect the stemness and heterogeneity of tumor cells, thus playing a carcinogenic role." (PMID 36199577, 2022). "Therefore, this study aimed to perform bioinformatics analysis to examine the correlation of ANLN with tumor immune infiltration, immune evasion, tumor progression, immunotherapy, and tumor prognosis." (PMID 35991576, 2022). "It seems that ANLN could skew the differentiation of Th1 cells towards the Th2 phenotype, which means shifting the immune response from antitumor to tumor-promoting." (PMID 36199577, 2022). "Furthermore, patients with a high TNM stage (TNM III–IV) or a high tumour grade showed high levels of ANLN expression, indicating that this gene can be used as an indicator of the malignant phenotype." (PMID 36312898, 2022). "Similarly, the association of ANLN expression with patient DFI was also investigated, demonstrating that ANLN expression influenced six tumor types, including PAAD, KICH, BRCA, KIPP, LIHC, and THCA." (PMID 35340220, 2022). "Previous reports indicated that ANLN could promote tumor progression through its well-studied function as a scaffold protein in regulating cytokinesis." (PMID 35340220, 2022). "We conjured that ANLN was dysregulated and highly expressed during tumor formation." (PMID 36199577, 2022). "Existing studies have shown that ANLN is necessary for tumor growth." (PMID 35340220, 2022). "Also, our data proved that the expression levels of circ-MMP11 and ANLN were significantly decreased in tumor tissues derived from the sh-circ-MMP11 groups relative to the sh-NC groups, while miR-153-3p expression presented an opposite trend in this xenograft." (PMID 34295807, 2021). "In HCC, miR-15a and miR-16-1 could bind to complementary sites in the 3'-UTRs of ANLN to inhibit tumor growth and predict favorable survival outcome." (PMID 34367283, 2021). "ANLN expression was significantly higher in tumor tissues than in adjacent normal control tissues." (PMID 34082790, 2021). "In summary, our findings demonstrate that the coordinate regulatory networks of alternatively spliced ANLN isoforms in HNSCC tumor growth and development, which might highlight the perspective for therapeutic strategies of HNSCC." (PMID 34344861, 2021). "The pathogenesis of ANLN in tumor progression might act as a cell cycle regulator, enabling the promotion of tumor growth by decreasing apoptosis and DNA damage, though the detailed mechanisms require further investigation." (PMID 32966237, 2020). "Therefore, considering the role of the ANLN in the nerve, it is expected that ANLN will also play a role in contributing to the nerve elements in tumour progression." (PMID 32560530, 2020). "ANLN mRNA levels were upregulated in human HCC tissues compared to non-tumor liver tissues." (PMID 31392101, 2019).
tumor (continued). "To address this issue, we confirmed that in 436 liver samples obtained from surgically removed HCC tissues, higher ANLN expression was detected in tumor tissues than in adjacent non-tumor tissues of HCC as measured by immunohistochemistry, quantitative real-time PCR and western blotting." (PMID 30103211, 2018). "With a median follow-up of 27.9 months, patients with high ANLN expression in tumor showed significantly poorer CSS (median, 22.4 vs. 37.3 months, p = 0.001), PFS (median, 19.7 vs. 27.9 months, p = 0.001) and RFS (median, 17.1 vs. 25.2 months, p = 0.011) compared with patients with low expression." (PMID 28600503, 2017). "ANLN expression level was always lower in normal urothelium that could be studied adjacent to tumor tissue (staining score,1.21 ± 0.59) than in tumor tissues (staining score, 3.57 ± 1.1, p < 0.001)." (PMID 28600503, 2017). "The fraction of ANLN positive tumor cells varied but the majority of cases showed a NF < 25%." (PMID 27863473, 2016). "Our findings suggest that miR-497 acts as a tumor suppressor by targeting ANLN and HSPA4L in NPC." (PMID 26486082, 2015). "In addition to discovering the crucial role of ANLN in cytokinesis via RhoA activation, we also illustrated that ANLN restrained the Hippo pathway by enhancing the activity of RhoA signaling, which together contributed to ANLN-mediated tumor-promoting effects on ICC." (PMID 41513610, 2026). "Furthermore, high ANLN expression has been linked to clinical features such as serum α-fetoprotein levels ≥400 μg/L and tumor diameter ≥8 cm, but it is not significantly correlated with age, tumor number, or differentiation grade." (PMID 41573677, 2025). "Thus, we assumed that ANLN might participate in the host anti‐tumor immune response by inducing M1 macrophages infiltration." (PMID 36030492, 2023). "Overall, the expression of ANLN was found to be associated with the infiltration levels of CD8+ T cells in 13 tumor types, CD4+ T cells in 20 tumor types, B cells in 20 tumor types, macrophages in 20 tumor types, neutrophils in 26 tumor types, and NK cells in 15 tumor types." (PMID 35568883, 2022). "Overall, our results indicated that aberrant ANLN expression could alter tumor immunity." (PMID 35568883, 2022). "Targeting ANLN might be an attractive approach to tumor treatment." (PMID 36199577, 2022). "However, the role of ANLN as an immunomodulatory gene in tumours has rarely been studied." (PMID 36312898, 2022). "In addition, ANLN was abundantly expressed in the tumor cell lines CAL27 and HN30." (PMID 34082790, 2021). "Moreover, there is an association between PI3K/AKT and the stability of ANLN in the nucleus and the activation of PI3K/AKT in the tumour could increase the VEGF level." (PMID 32560530, 2020). "Knocking down ANLN could significantly decrease the invasiveness and growth of tumor cells." (PMID 31636652, 2019). "Thus, we conclude that ANLN promotes tumor growth by ways of decreased apoptosis and DNA damage." (PMID 30103211, 2018). "Multivariable analysis showed that the association between ANLN and survival was significantly independent of age in cohort I and significantly independent of proliferation, as assessed by Ki-67 expression in tumor cells, age, tumor size, ER and PR status, HER2 status and nodal status in cohort II." (PMID 27863473, 2016). "Here, we illustrated that ANLN restrains the Hippo pathway by reducing YAP1 phosphorylation level and enhancing YAP1 transcriptional activity, partly explaining the promoting-tumor effects of ANLN in ICC." (PMID 41513610, 2026). "For further verification, ANLN mRNA and protein levels were assessed in ICC tumors and corresponding non-tumor adjacent tissues." (PMID 41513610, 2026). "Here, our findings identified the ANLN/RhoA/YAP1/TEAD1 positive feedback axis in ICC, which was essential for cytokinesis and tumor growth." (PMID 41513610, 2026).